LGR5 (leucine rich repeat containing G protein-coupled receptor 5)
Diseases named in the same sentence as LGR5 in open-access papers (continued):
Sharing a sentence is not in itself a finding about the gene and the disease.
colorectal cancer (continued). "Such an implication of LGR5-negative cells in colorectal cancer dissemination points to the limitation of using protein markers to assess CSC activity." (PMID 37894295, 2023). "However, another report suggests that αSMA+ CAFs promote the differentiation of colorectal cancer stem cells through the BMP4/TGFβ1 signaling pathway, thereby inhibiting Lgr5+ CSCs." (PMID 37124519, 2023). "Among these targets, MUC1 was characterized as a stemness driver in colorectal cancer where MUC1 forms a complex with MYC transcriptional factor and activates the expression of leucine-rich repeat-containing G protein-coupled receptor 5 (LGR5) gene, a marker of the intestine stem cells and CSCs." (PMID 36900399, 2023). "In conclusion, through the sorting and analysis of the radiation resistance projects in the GEO database and tumor vs. normal tissue project in TCGA-COREAD database, we established a gene panel (LGR5, KCNN4, TNS4 and CENPH) in colorectal cancer patients receiving radiotherapy." (PMID 37328854, 2023). "For example, the major population of circulating cancer cells during metastasis in colorectal cancer are negative for Lgr5, a cancer stem-like cell marker, or Lgr5-non-cancer stem cells." (PMID 37838167, 2023). "Among the top genes emerging from limma analysis, we found four genes particularly related to cancer stemness and CRC CSCs: besides the pluripotency factor KLF4, we found three genes were specifically related to colorectal cancer stemness and self renewal, i.e., AXIN2, LGR5 and BMI1." (PMID 36077264, 2022). "They showed that selective ablation of Lgr5+ tumour stem cells from colorectal cancer limits the growth of the primary tumour but does not lead to tumour regression." (PMID 35563449, 2022). "Moreover, GBZ strongly reduced the expression of β-catenin target genes at the protein level (AXIN2) and mRNA level in colorectal cancer cells (AXIN2, LGR5)." (PMID 35115535, 2022). "Curcumin can suppress oncogenicity of many cancer cells, yet the effect and mechanism of curcumin in LGR5(+) colorectal cancer stem cells (CSCs) have not been studied." (PMID 33713277, 2021). "Stemness markers reported for colorectal cancer stem cells include CD133, CD44, LGR5 and ALDH1A1." (PMID 34148069, 2021). "A number of CSC markers linked to colorectal cancer (CRC) have been described, including, but not restricted to, epithelial cell adhesion molecule (EpCAM), and leucine-rich repeat-containing G protein-coupled receptor 5 (LGR5)." (PMID 35008827, 2021). "LGR5 is a marker of colorectal CSCs; a recent colorectal cancer study showed that LGR5 negative cells can become CSCs and lead to metastasis." (PMID 32850862, 2020). "The overexpression of Lgr5 in the colorectal cancer cells occurs due to up or downregulation of several noncoding RNAs, such as CASC15 miR-4310 or miR-23a, as a consequence of activation of PI3K/Akt signaling pathway." (PMID 32671503, 2020). "Indeed, poor differentiated histology is significantly associated with HOPX silencing by its promoter methylation in colorectal cancer, and HOPX represents +4 quiescent intestinal stem cells which can interconvert between Lgr5+ active stem cells." (PMID 31666923, 2019). "Lgr5 and OLFM4 tracing proved that colorectal cancer originated from Lgr5+ intestinal stem cells." (PMID 30310855, 2018). "Importantly, SFN inhibits Wnt/β-catenin signaling in colorectal cancer cells as shown by inhibition of β-catenin-dependent luciferase reporters and repression of β-catenin target genes (AXIN2, LGR5)." (PMID 30338040, 2018).
colorectal cancer (continued). "Colorectal cancer (CRC) stem cells express CD44, CD133, CD166, CD24, CD66c, CD29, the epithelial cell adhesion molecule, Musashi-1, aldehyde dehydrogenase-1 (ALDH1), and the leucine-rich-repeat containing G protein-coupled receptor 5 (LGR5)." (PMID 28604612, 2017). "Lgr5+ colorectal cancer cells have higher tumorigenic and clonogenic abilities than Lgr5-negative colorectal cancer cells in xenotransplantation and/or organoid formation assays." (PMID 29064439, 2017). "Lgr5, a member of the GPCR superfamily, is overexpressed in many types of human cancer including esophageal adenocarcinoma, gastric cancer, and colorectal cancer." (PMID 28404940, 2017). "To determine if they directly induce distinct embryonic and intestinal SC programs, we expressed KRASmut, LGR5, and pCCL control lentiviral vectors in SW48 cells, which harbored KRASwt and had LGR5 expression in the lower quartile of human colorectal cancer cells." (PMID 26744320, 2016). "Our data suggests that lgr5 methylation, through the regulation of lgr5 expression and colorectal CSC differentiation, may constitute a novel prognostic marker for colorectal cancer patients." (PMID 26599100, 2015). "In our study, we also observed positive lgr5 promoter methylation in approximately 40% of colorectal cancers, and verified that negative lgr5 expression was significantly associated with the promoter DNA methylation." (PMID 26599100, 2015). "Interestingly, PGE2 has been shown to potentiate the WNT signaling cascade, both in colorectal cancer cells, as well as in normal adult hematopoietic stem cells, and it was recently found that PGE2 upregulates LGR5." (PMID 24252460, 2013). "In colorectal cancer (CRC), lineage tracing and ablation experiments demonstrated that even upon elimination of LGR5+ CSCs, LGR5− tumor cells could regenerate the CSC pool, emphasizing that CSC identity is plastic and regulated by both intrinsic and extrinsic cues." (PMID 41002429, 2025). "In colorectal cancer, EphA2 and EphB2, belonging to the tyrosine kinase receptor family, have been identified as novel markers for colorectal CSCs, whose expression is strongly correlated with the expression of CD44 and Lgr5, as well as the stemness of colorectal cancer cells." (PMID 41346572, 2025). "Interestingly, most colorectal cancer circulating metastasis-initiating cells are LGR5-negative despite holding clear tumor-initiating capacities." (PMID 37894295, 2023). "According to a recent report, Bandara and colleagues developed a panel of six different LGR5-redirected CAR-T products and demonstrated that four of these products were capable of mediating meaningful tumoricidal effects in vitro against cell lines of colorectal cancer." (PMID 38146364, 2023). "Likewise, in a model system, LGR5-negative (i.e., with low Wnt signaling) colorectal cancer cells with high plasticity were found to drive metastasis." (PMID 35536676, 2022). "Therefore we considered whether a relationship exists between LGR5 and YAP-TEAD in HSCC just like it is in colorectal cancer." (PMID 36288272, 2022). "Our findings demonstrate that bufalin can significantly inhibit colorectal cancer stemness and tumorigenesis, which is accompanied by its activity against EMT markers (Slug, ZEB1, N-Cadherin) and functional stem cell markers (CD44, CD133, LGR5, ALDH, and pluripotency factors)." (PMID 36362141, 2022). "However, most of the papers point out that ROS-mediated LGR5 transcription and ISCs expansion are connected to colorectal cancer initiation, not physiological turnover." (PMID 36421992, 2022). "As AMBRA1 affected CTNNB1 transcription via ALDH1B1, which is a crucial CSC marker of colorectal cancer, we next investigated whether AMBRA1 expression affects the mRNA levels of several CSC-related β-catenin target genes, including LGR5, HIF1a, ALDH1A3, CD24, and SOX4." (PMID 34769507, 2021).
colorectal cancer (continued). "In a mouse colorectal cancer model with CSCs marked with diphtheria toxin receptor (DTR) under control of the Lgr5 promoter, addition of diphtheria toxin ceased tumor growth as a result of ablation of Lgr5+ CSCs; diphtheria toxin removal reproduced Lgr5+ CSCs and resulted in tumor regrowth." (PMID 31336602, 2019). "Moreover, studies with colorectal cancer showed a negative effect in the overall patients’ survival if LGR5 is overexpressed." (PMID 29190952, 2017). "However, to our knowledge, the relationship between the expression of Lgr5 and the expression of Ki-67 in colorectal carcinoma has not yet been investigated." (PMID 23153436, 2012). "While LGR5 may well mark the colorectal cancer stem cells, our data suggest that LGR5 is not functionally required for tumour expansion but may instead play a role in stem cell localization and restriction to a self-renewing niche." (PMID 21829496, 2011). "Whether these cancer stem cells are able to upregulate Lgr5 expression in a BMAL1 independent manner and how BMAL1, MEX3A and Lgr5 regulatory relationship in colorectal cancer stem cells differs from that in non-cancerous intestinal tissue will also be of interest for further investigation." (PMID 37845346, 2023). "To further investigate whether the Lgr5+ cells in human GAs had any stem cell properties, we analyzed the levels of ISC markers such as ASCL2, EPHB2, and OLFM4, which are highly expressed in stem-like cells from human colorectal cancers, as well as in murine intestinal adenomas." (PMID 24340024, 2013). "By detecting RNA level of LNX1 of the sorted SP and non-SP from the colorectal carcinoma cell line HT29, it was found that LNX1 was highly expressed in SP cells with higher levels of LGR5, ABCB5, ALDH1A1 and CD133 rather than non-SP group." (PMID 29190716, 2017). "Interestingly, we did not observe an overlap between AF and LGR5+ cells in colorectal cancer tumors, suggesting that AF cells represent a distinct CSC population in colorectal cancer like EMP1+ cells." (PMID 39225547, 2024).
colon carcinoma (199 papers, 2008 to 2026). "Organoids derived from colonic tumors carrying Cdx1 and Cdx2 mutations exhibited increased proliferation and elevated Lgr5 expression levels." (PMID 40399276, 2025). "LGR5 was initially identified as a WNT target gene in human colon cancer and especially in those that harbored WNT-activating mutations." (PMID 37770230, 2023). "In our study, we found that the reduced ability of colon cancer with inhibited PCs activity to mediate tumor growth was associated with reduced expression of the CSC markers LGR5 and NANOG." (PMID 35267511, 2022). "In this study, we revealed that the malignant phenotype of colon cancer stem cells is repressed by Furin inhibition that is associated with reduced expression of LGR5 and Nanog and dysregulated expression of several calcium regulators involved in colon cancer." (PMID 35267511, 2022). "Further analysis revealed that reduced tumor growth mediated by specific silencing of the convertase Furin in KRAS or BRAF mutated-induced colon tumors was associated with reduced expression of LGR5 and NANOG compared to wild-type KRAS and BRAF tumors." (PMID 35267511, 2022). "The proximal colonic tumours that develop in this model exhibit a foetal-like progenitor phenotype (Ly6a/Sca1+) and, importantly, lack expression of Lgr5 and its associated intestinal stem cell signature." (PMID 34103493, 2021). "In colon cancer, the percentage of LGR5-expressing cells has been reported to be associated with different background of the tumors, especially the accumulation of certain oncogenic mutations." (PMID 32327656, 2020). "Cells expressing leucine-rich repeat-containing G-protein coupled receptor 5 (Lgr5) constitute a cancer-causing population in the colon; therefore, targeting of Lgr5+ cells is expected to provide an opportunity to mitigate colon cancer." (PMID 31947553, 2020). "Both adiponectin and AdipoRon, a small molecule adiponectin receptor agonist, were found to suppress colon cancer risk in part by reducing the number of leucine-rich repeat-containing G protein-coupled receptor 5+ (Lgr5+) stem cells in mouse colonic organoids." (PMID 33167521, 2020). "LGR5 ablation in colon cancer cells and crypt stem cells resulted in loss of cortical F-actin, reduced cell–cell adhesion, and disrupted localization of adhesion-associated proteins." (PMID 28739799, 2017). "Consistent with a prior study, we found that stage I colon carcinomas that expressed LGR5 (LGR5+; n= 10) significantly associated with the intestinal SC signature when compared to those that did not express LGR5 (LGR5−; n= 7)." (PMID 26744320, 2016). "Our findings demonstrate for the first time that rapidly cycling Lgr5+ stem cells are exquisitely sensitive to extrinsic dietary factors which modulate colon cancer risk." (PMID 27831561, 2016). "Recent studies have demonstrated that a high LGR5 expression in colon cancer tissues was closely associated with increased lymph node invasion, distant metastasis and poor chemotherapy response." (PMID 24789370, 2014). "A higher expression of LGR5 has been found in colon cancer and adenomas relative to matched normal mucosa, and is associated with malignant clinicopathological characteristics, suggesting that LGR5 is involved in tumor development and progression." (PMID 24789370, 2014). "CD31 expression is associated to CD133 or Lgr5 expression in colon cancer tissues, which indicates robust angiogenesis is stimulated by cancer stem cells." (PMID 22745705, 2012). "Similarly, the same association as CBLL1 was found for the LGR5 gene, a cancer stem cell biomarker in colon cancer, as well as with the transcription factor c-MYC, which is a well-known universal marker of CSCs." (PMID 38339195, 2024).
colon carcinoma (continued). "With further development, the targeting of localized Lgr5+ cancer stem cells, which this study demonstrates in concept, may be feasible for prevention of colon cancer in high-risk populations." (PMID 31947553, 2020). "Additionally, GP significantly decreased CD133 with a mild effect on LGR5 (the downregulation of CD133 and LGR5 is linked with growth inhibition of colon cancer cells) in normal colonic mucosa." (PMID 33202681, 2020). "A recent publication has demonstrated that down-regulation of c-kit in colon cancer cell lines increased expression of leucine-rich repeat-containing G-protein coupled receptor 5 and its associated genes, which are involved in the formation of cancer-stem/progenitor cells." (PMID 28055980, 2017). "For example, LGR5-targeted antibody–drug conjugates were demonstrated to induce cytotoxicity in LGR5-high gastrointestinal cancer cells and decrease tumor size and proliferation in colon cancer xenograft models." (PMID 40076613, 2025). "The expression patterns of MUC2 and LGR5 differ between the colon cancer cell line (Caco-2 cells) and colon organoids, highlighting the limitations of using 2D cultures as a model for studying viral infection." (PMID 40836050, 2025). "Target genes of this pathway, including CD44, CD133, Lgr5, EpCAM and c-Myc, are frequently used as markers of colon cancer-initiating cells." (PMID 40259095, 2025). "For example, Wnt5a has been shown to decrease Lgr5/RSPO3 expression and β-catenin activity in vitro, and its expression has been associated with improved survival in colon cancer." (PMID 41008809, 2025). "In adult intestinal crypts and colon cancer LGR5 marks cycling crypt base columnar cells, which are considered as true intestinal stem cells capable of differentiating into all types of intestinal epithelial cells." (PMID 41194856, 2025). "Different approaches have been used to target Lgr5+ cells and have been successful in reducing cell proliferation; however, cancer stem cell plasticity remains an obstacle in treating colon cancer." (PMID 39183418, 2024). "They found that most of the circulating colon cancer cells were LGR5− and in contrast the cells in the metastases were LGR5+ CSCs.This finding emphasizes the unique role that CSCs play in the growth of primary and metastatic tumors." (PMID 39547513, 2024). "LGR5 is a well-known stem cell marker that is a regulator of the Wnt pathway and is overexpressed in different human carcinomas (e.g., colon cancer, glioblastoma, and oral squamous cell carcinoma (OSCC))." (PMID 39769183, 2024). "According to the results of bioinformatics analysis, the top five differentially expressed genes in tissue stem cells and a colon cancer stem cell marker (LGR5) were further verified in primary (n = 18) and metastatic (n = 18) lesions." (PMID 39382748, 2024). "The ablation of Lgr5-expressing cells in primary colon tumors inhibited metastasis whereas the growth of primary tumors quickly recovered by dedifferentiation of non-stem cells into Lgr5-expressing stem cells." (PMID 38659853, 2024). "According to one study, colon cancer cells can dedifferentiate into CSCs when they acquired the LGR5+ phenotype." (PMID 39547513, 2024). "We have recently reported that DKK2 enhanced Lgr5 expression in colon cancers through activation of c-Src." (PMID 38659853, 2024). "Another study also showed that Notum was specially expressed in slow-cycling LGR5+ cells from xenografted human colon tumors and was upregulated in colon cancer clinical specimens." (PMID 37749430, 2024). "Unlike wild-type CRC, knockouts selectively showed increased populations of Lgr5+ colon cancer stem-like cells." (PMID 39456736, 2024). "We show a similar behaviour for the CSC biomarker LGR5 in the same cohort of CMS2 colon cancer patients." (PMID 38339195, 2024).